NKD2 (NKD inhibitor of Wnt signaling pathway 2)
Description:
Cell autonomous antagonist of the canonical Wnt signaling pathway. May activate a second Wnt signaling pathway that controls planar cell polarity (By similarity). Required for processing of TGFA and for targeting of TGFA to the basolateral membrane of polarized epithelial cells.
Synonyms: Naked2
Tractability: Antibody: UniProt places it where antibodies can reach, with high confidence; its Gene Ontology location is reachable by antibodies, with high confidence. PROTAC: UniProt records ubiquitination sites on it; ubiquitination databases record sites on it.
Gene: Protein-coding gene on chromosome 5 (1,008,021 to 1,040,630, forward strand). Ensembl gene ENSG00000145506.
Subcellular location: Cell membrane; Cytoplasm; Cytoplasmic vesicle
Pathways (Reactome):
Chromatin organization: CHD6, CHD7, CHD8, CHD9 subfamily
Gene Ontology:
Molecular function: ATPase binding; growth factor binding; molecular adaptor activity; myosin heavy chain binding; protein binding; ubiquitin protein ligase binding; calcium ion binding
Biological process: Golgi vesicle fusion to target membrane; negative regulation of canonical Wnt signaling pathway; positive regulation of proteasomal ubiquitin-dependent protein catabolic process; positive regulation of protein localization to plasma membrane; positive regulation of protein processing; protein localization to plasma membrane; vesicle fusion to plasma membrane; negative regulation of Wnt signaling pathway
Cellular component: basolateral plasma membrane; cell periphery; cytoplasm; cytoplasmic vesicle; exocytic vesicle; lateral plasma membrane; plasma membrane; cytosol
Genetic constraint (gnomAD): Loss-of-function variants: 42 observed, 32.09 expected, observed/expected ratio (o/e) 1.31, 90% interval 1.02 to 1.69. The upper end of that interval is the gene's LOEUF score, 1.69, which puts it in group 6 of 6, group 1 being the genes least tolerant of losing a copy. Missense variants: 657 observed, 551.9 expected, observed/expected ratio (o/e) 1.19, 90% interval 1.12 to 1.27. Synonymous variants: 274 observed, 232.05 expected, observed/expected ratio (o/e) 1.18, 90% interval 1.07 to 1.3.
Homologues: Orthologues: chimpanzee NKD2 (95% identical), macaque NKD2 (95% identical), rat Nkd2 (78% identical), mouse Nkd2 (78% identical), pig NKD2 (75% identical), guinea pig NKD2 (71% identical), dog NKD2 (66% identical), zebrafish nkd2a (46% identical), zebrafish nkd3 (35% identical), Drosophila melanogaster nkd (25% identical), Drosophila melanogaster PIP82 (21% identical). Paralogues in human: NKD1 (43% identical).
Diseases named in the same sentence as NKD2 in open-access papers:
NKD2 is named in the same sentence as 27 diseases in open-access papers, as found by Europe PMC text mining. Sharing a sentence is not in itself a finding about the gene and the disease. The quoted sentences say what the papers report.
breast carcinoma (13 papers, 2007 to 2025). "NKD2 promoter methylation, associated with a reduction of NKD2 expression and activation of Wnt/β-catenin signaling, has been observed in more than 50% of human primary breast cancer samples." (PMID 27420097, 2016). "NKD2 methylation may serve as a breast cancer diagnostic and prognostic marker." (PMID 26124080, 2015). "NKD2 is an adapter protein and endogenous inhibitor of Wnt‐β‐catenin signaling and has been described to reduce breast cancer cell proliferation and tumor and metastasis growth in osteosarcoma patients." (PMID 40762106, 2025). "The ectopic expression of LINC00922 has been found to induce the EMT process in breast cancer cells by targeting NKD2." (PMID 36613528, 2022). "First, experiments using ectopic expression of Linc00922 revealed that it increases tumor growth in xenograft mouse models of breast cancer through inhibition of NKD2, thereby enhancing breast cancer metastasis to the lung and the liver." (PMID 36139687, 2022). "This is indeed critical, as NKD2 is often methylated and poorly expressed in breast cancer while it also antagonizes the Wnt signaling pathway, suppressing tumor growth and metastasis." (PMID 36139687, 2022). "To further explore the effects of NKD2 on breast cancer cell growth, we employed a MDA-MB-231 xenograft mouse model in which NKD2 was either stably expressed or unexpressed." (PMID 26124080, 2015). "Our study demonstrated that NKD2 was frequently methylated in human breast cancer and its expression was regulated by promoter region methylation." (PMID 26124080, 2015). "NKD2 staining was observed in the cytoplasm of the adjacent tissue samples and its expression was significantly reduced in primary breast cancer samples." (PMID 26124080, 2015). "In conclusion, NKD2 is frequently methylated in human breast cancer, and the expression of NKD2 is regulated by promoter region methylation." (PMID 26124080, 2015). "The expression of NKD2 was evaluated by immunohistochemistry (IHC) in 30 cases of available matched breast cancer and adjacent tissue samples." (PMID 26124080, 2015). "Through our in vitro and in vivo studies, it was validated that NKD2 suppresses breast cancer cell growth by inhibiting Wnt signaling." (PMID 26124080, 2015). "In conclusion, NKD2 is frequently methylated in human breast cancer and its expression is regulated by promoter region methylation." (PMID 26124080, 2015). "The aim of this study is to investigate the epigenetic changes and mechanisms of NKD2 in human breast cancer development." (PMID 26124080, 2015). "The expression of NKD1 and NKD2 was regulated by promoter region methylation in breast cancer cells." (PMID 26124080, 2015). "Similarly, lncRNA 00922 recruited three DNMTs in the NKD2 promoter to trigger NKD2 methylation and repress its expression, contributing to activation of Wnt signaling pathway and breast cancer progression." (PMID 35620052, 2022). "Moreover, the latest study identified that LINC00922 regulated EMT in breast cancer through promoting NKD2 methylation." (PMID 34116704, 2021). "Overexpression of NKD2, a negative regulator of Wnt signaling, in metastatic osteosarcoma and breast carcinoma significantly reduces tumor growth and metastasis in vivo and decreases cell proliferation, migration and invasion in vitro, while down-regulation has the opposite effect." (PMID 27144453, 2016). "The results suggest that NKD2 is a tumor suppressor in human breast cancer." (PMID 26124080, 2015). "NKD2 suppresses breast cancer cell growth by inhibiting Wnt signaling both in vitro and in vivo." (PMID 26124080, 2015). "NKD2 suppressed breast cancer cell proliferation both in vitro and in vivo." (PMID 26124080, 2015). "Our study found NKD2 is methylated in 51.4% of breast cancer." (PMID 26124080, 2015). "NKD2 suppresses breast cancer proliferation by inhibiting Wnt signaling." (PMID 26124080, 2015). "In this study, we studied the epigenetic regulation and function of NKD2 in breast cancer." (PMID 26124080, 2015).
breast carcinoma (continued). "NKD2 was methylated in 51.4% (35/68) of human primary breast cancer samples." (PMID 26124080, 2015). "NKD2 induced G1/S arrest and inhibited Wnt signaling in breast cancer cells." (PMID 26124080, 2015). "It indicates that NKD2 methylation may serve as a breast cancer prognostic marker." (PMID 26124080, 2015). "Mechanistically, LINC00922 recruited DNA methylases to the promoter of naked cuticle homolog 2 (NKD2), which induced the aberrant methylation of NKD2, helping to enhance the migratory and invasive ability of breast cancer cells." (PMID 36613528, 2022). "NKD2, one of the naked cuticle (NKD) family, is frequently methylated and suppresses proliferation by inhibiting Wnt signaling in human breast cancer." (PMID 27246976, 2017). "Additionally, Naked cuticle homolog 2 (NKD2) is commonly methylated in gastric and breast carcinoma." (PMID 34488905, 2021). "As NKD1 methylation did not appear to be a major event in human breast cancer, we mainly focused on the mechanisms of NKD2 in breast carcinogenesis." (PMID 26124080, 2015). "NKD2 was methylated in 51.4% (35/68) of primary breast cancer samples, and no methylation of NKD2 was detected in normal breast tissue samples." (PMID 26124080, 2015). "The results from the analysis of six breast cancer cell lines and two normal breast epithelial cell samples indicated that 7 of 12 genes (RIL, HIN-1, RASSF1A, ARHI, CDH13, RARβ2, and NKD2) were densely methylated (marked bold) in cancer cell lines but not in normal breast epithelial cell lines." (PMID 17764565, 2007).
osteosarcoma (12 papers, 2015 to 2025). A usually aggressive malignant bone-forming mesenchymal neoplasm, predominantly affecting adolescents and young adults. "Another study revealed that miR-130b targeted naked cuticle homolog 2 (NKD2) and regulated the Wnt signaling pathway, promoting proliferation and inhibiting apoptosis of osteosarcoma cells." (PMID 33628370, 2021). "NKD2 expression was found to suppress tumor growth and to be downregulated in human metastatic osteosarcoma cells." (PMID 29263426, 2017). "In osteosarcoma, NKD2 decreases the proliferative and metastatic properties." (PMID 36820951, 2023). "Additionally, the role of NKD2 involving development, progression, or prognosis in several tumors has been demonstrated, like glioma, lung cancer, osteosarcoma, and gastric cancer." (PMID 36348408, 2022). "Based on the mechanistic studies regarding osteosarcoma pathogenesis, it seems that the canonical Wnt signaling pathway is involved in osteosarcoma progression possibly through naked cuticle homolog 2 (NKD2) which negatively regulates the Wnt/β-catenin pathway." (PMID 35676319, 2022). "In addition, it has been documented that NKD2 played important roles in the development of several tumors, like glioma, lung cancer, osteosarcoma, and gastric cancer." (PMID 36348408, 2022). "Nevertheless, a study has described that naked cuticle homolog 2 (NKD2), a negative regulator of Wnt signaling, downregulates the expression of genes involved in the vasculature development of osteosarcoma, suggesting a pro-angiogenic role of the Wnt/β-catenin pathway in osteosarcoma." (PMID 31370265, 2019). "In addition, NKD2 suppresses tumor growth and metastasis in osteosarcoma by function as a negative regulator of Wnt signaling, which is critical for driving metastatic potential." (PMID 27246976, 2017). "Overexpression of NKD2 in osteosarcoma cell line decreased proliferation, migration, and invasion in vitro and diminished tumor growth and metastasis in vivo, consistent with a model wherein Wnt signaling potentiates these aggressive behaviors in osteosarcoma." (PMID 27049730, 2016). "Recent study suggested that NKD2 is a tumor suppressor in osteosarcoma." (PMID 26124080, 2015). "NKD2 could suppress the cell growth and tumor metastasis of osteosarcoma." (PMID 36348408, 2022). "The role of NKD2 and its inhibitory impact on the WNT signaling pathway has previously been documented in the context of suppressing tumor growth and metastasis in osteosarcoma, colorectal carcinoma, and acute myeloid leukemia." (PMID 40762106, 2025).
gastric cancer (10 papers, 2010 to 2022). A primary or metastatic malignant neoplasm involving the stomach. "The knockdown of ZFAS1 causes increase in gastric cancer sensitivity to paclitaxel by suppressing the NKD2 leading to induction of Wnt negative regulator, thus leading to the induction of Wnt/Β-Catenin pathway." (PMID 35582574, 2019). "NKD2 is located in chromosome 5p15.3, and loss of heterozygosity is frequently found in this region in colorectal and gastric cancer." (PMID 26396173, 2015). "The expression of SOX18 is associated with NKD2 methylation significantly in primary gastric cancer." (PMID 26396173, 2015). "To further validate SOX18 is regulated by NKD2, we analyzed the association between SOX18 overexpression and NKD2 methylation in human primary gastric cancer." (PMID 26396173, 2015). "NKD2 methylation may serve as a gastric cancer diagnostic, prognostic and chemo-sensitive marker." (PMID 26396173, 2015). "Dysregulation of NKD2 has been suggested to be involved in tumorigenesis of multiple cancers, including gastric cancer, esophageal cancer, and HCC, among others." (PMID 33557409, 2021). "ZFAS1 is able to regulate gastric cancer sensitivity by decreasing NKD2 and activating the Wnt/Β-Catenin pathway." (PMID 35582574, 2019). "In order to understand the mechanism of NKD2 in gastric cancer development, 6 gastric cancer cell lines and 196 cases of human primary gastric cancer samples were involved." (PMID 26396173, 2015). "The role of NKD2 in gastric cancer progression and metastasis was further studied both in vitro and in vivo." (PMID 26396173, 2015). "The expression of NKD2 was evaluated by IHC in 47 cases of available matched gastric cancer and adjacent tissue samples." (PMID 26396173, 2015). "Methylation of NKD1 and NKD2 was examined in 196 cases of primary gastric cancer and 28 cases of normal gastric mucosa." (PMID 26396173, 2015). "NKD1 and NKD2 were methylated in 11.7% (23/196) and 53.1% (104/196) in human primary gastric cancer samples." (PMID 26396173, 2015). "The results suggest that the expression of SOX18 is regulated by NKD2 in human primary gastric cancer." (PMID 26396173, 2015). "NKD2 was methylated in 53.1% (104/196) of human primary gastric cancer samples, and methylation of NKD2 was significantly associated with the degree of cell differentiation, TNM stage and distant metastasis (all P < 0.05)." (PMID 26396173, 2015). "In conclusion, NKD2 is frequently methylated in human gastric cancer, and methylation of NKD2 is involved in gastric carcinogenesis." (PMID 26396173, 2015). "In this study, we detected the methylation status of NKD1 and NKD2 in human gastric cancer cell lines and primary cancer tissue samples." (PMID 26396173, 2015). "The expression of NKD2 was apparently reduced in 20 cases of gastric cancer tissue samples compared to adjacent tissue samples." (PMID 26396173, 2015). "The mechanisms of NKD2 in gastric cancer cell invasion and migration were further investigated by detecting the expression of MMP-2 and MMP-9." (PMID 26396173, 2015). "Katoh investigated the expression of NKD1 and NKD2 in human cancer cell lines and primary gastric cancer." (PMID 20828404, 2010). "Here, our findings also showed that NKD2 could function as a tumor suppressor and its overexpression impaired gastric cancer cells proliferation." (PMID 27246976, 2017). "Re-expression of NKD2 sensitized gastric cancer cells to docetaxel." (PMID 26396173, 2015). "The growth of gastric cancer xenografts was suppressed by NKD2." (PMID 26396173, 2015). "In conclusion, NKD2 methylation may serve as a poor prognostic and chemo-sensitive marker in human gastric cancer." (PMID 26396173, 2015). "Down-regulation of SOX18 by NKD2 was validated by RT-PCR and western blot in gastric cancer cells." (PMID 26396173, 2015). "NKD2 suppresses gastric cancer metastasis by down-regulating SOX18 and its downstream genes." (PMID 26396173, 2015).
gastric cancer (continued). "NKD1 was infrequently methylated in primary gastric cancer, while NKD2 was frequently methylated." (PMID 26396173, 2015). "Besides, NKD2 has been frequently methylated in human breast cancer and gastric cancer." (PMID 36348408, 2022). "To further determine whether KLF2 and NKD2 is involved in the ZFAS1 induced promotion of gastric cancer cells proliferation, we detected their expression in 20 pairs gastric cancer and normal tissues and found that their expression are both decreased in gastric cancer tissues." (PMID 27246976, 2017). "Moreover, we conducted rescue assays to determine whether KLF2 and NKD2 involved in ZFAS1 contributions to gastric cancer cell proliferation." (PMID 27246976, 2017). "The overall survival was longer in the NKD2 unmethylation group compared to the NKD2 methylation group (P < 0.05), suggesting that NKD2 methylation is related to tumor malignancy, progression and metastasis, and it may serve as a poor prognostic predictor in human gastric cancer." (PMID 26396173, 2015). "Therefore, we mainly focused our study on NKD2 in gastric cancer." (PMID 26396173, 2015). "Mechanistically, ZFAS1 was found to promote gastric cancer cell proliferation by inhibiting KLF2 and NKD2 expression." (PMID 28938617, 2017). "Further investigations determined that tumor suppressors NKD2 and KLF2 are novel ZFAS1 targets in gastric cancer cells." (PMID 27246976, 2017). "Above results suggest that NKD2 impedes cell invasion and metastasis by inhibiting SOX18 in gastric cancer." (PMID 26396173, 2015). "With regards to function, ZFAS1 has been shown to regulate cell proliferation and migration of ovarian cancer by targeting miR-150-5p, whereas, in gastric cancer, ZFAS1 was demonstrated to accelerate cell proliferation via repressing the expression of KLF2 and NKD2." (PMID 29416676, 2018). "To determine whether ZFAS1 repressed NKD2 and KLF2 expression via interacting with EZH2 or LSD1 in gastric cancer cells, we evaluated their expression after knockdown of EZH2 and LSD1 in gastric cancer cells." (PMID 27246976, 2017). "As NKD1 methylation did not appear to be a major event in human gastric cancer, we mainly focused on the mechanisms of NKD2 in gastric carcinogenesis." (PMID 26396173, 2015). "While, the COX regression analysis indicated that NKD2 methylation is not an independent prognostic factor in gastric cancer." (PMID 26396173, 2015). "Experiments in vivo also showed that knockdown of ZFAS1 inhibited the tumorigenic ability of gastric cancer cells, and mechanistic experiments validated that ZFAS1 could promote the proliferation of gastric cancer cells by inhibiting the expression of KLF2 and NKD2." (PMID 28938617, 2017). "In GC cells, a previous study found that long non-coding RNA ZFAS1 promoted gastric cancer cells proliferation by epigenetically repressing KLF2 and NKD2 expression." (PMID 29113337, 2017). "Furthermore, ZFAS1 expression is also overexpressed in gastric cancer, and its increased level is correlated with a shorter survival and poor prognosis and promotes the proliferation of gastric cancer cells by epigenetically repressing the KLF2 and NKD2 expression levels." (PMID 28154416, 2017).
colorectal cancer (6 papers, 2010 to 2025). A primary or metastatic malignant neoplasm that affects the colon or rectum. "Their findings showed that curcumin significantly inhibited the proliferation of colorectal cancer cells and upregulated the expression of NKD2 in the cells, which resulted in the downregulation of key markers in Wnt signaling." (PMID 34621313, 2021). "In colorectal carcinoma, downregulating NKD2 endows an oncogenic function." (PMID 36820951, 2023). "Naked cuticle homolog 2 (Nkd2) small-interfering RNA (siRNA) and chemokine receptor 4 (CXCR4) expression plasmid were synthesized and transfected into curcumin-treated SW620 colorectal cancer cell lines, and the NKD2 and CXCR4 expression levels were determined." (PMID 34621313, 2021).
esophageal cancer (5 papers, 2010 to 2021). A primary or metastatic malignant neoplasm involving the esophagus. "Further study showed that NKD2 attenuates the development of esophageal carcinoma through suppressing Wnt signaling in-vitro and in-vivo, suggesting that NKD2 methylation can potentially be used as a prognostic marker in esophageal carcinoma." (PMID 34488905, 2021). "NKD2 was methylated in 53.2% of esophageal cancer and silencing of NKD2 activated Wnt signaling to promote G1/S transition." (PMID 32974031, 2020). "In addition, silencing NKD2 can promote the progression of esophageal cancer by activating Wnt pathway in, which is similar to our findings." (PMID 32766227, 2020).